INS (insulin)
Diseases named in the same sentence as INS in open-access papers (continued):
Sharing a sentence is not in itself a finding about the gene and the disease.
Insulin resistance (continued). "Having confirmed the development of hepatic insulin resistance (impaired glucose tolerance and the blunted insulin-stimulated phosphorylation of Akt and GSK3β in the liver), we next investigated the involvement of JNK and IKK as mediators of steatosis and insulin resistance." (PMID 22355328, 2012). "Although we did not have data on insulin resistance in the HOST study, abnormalities in glucose and insulin metabolism likely play a role in the association between vitamin D and MetS in patients with CKD." (PMID 22784560, 2012). "Together, these observations strongly suggested that mitochondrial dysfunction, leading to lipid-induced insulin resistance is not the major mechanism accounting for reduced insulin sensitivity in rapamycin-treated myotubes." (PMID 22973301, 2012). "Nevertheless, 3-month-old obB1B2KO mice show similar insulin tolerance when compared to obWT mice, suggesting that differences in insulin resistance between these animals are age dependent and do not occur in younger mice." (PMID 22829877, 2012). "Thus, although the HFD-induced increase in the levels of insulin resistance markers is more marked in female rats than in males, HFD obese female rats still maintain a better serum profile of insulin sensitivity." (PMID 22353542, 2012). "Although fat tissue is not the main tissue responsible for insulin stimulated glucose uptake, it seems to be the major tissue responsible for induction of the whole body insulin resistance." (PMID 23054552, 2012). "Adaptation to the insulin resistance by increasing insulin secretion reaches a critical point in some individuals where they can no longer maintain insulin secretion at such high levels." (PMID 23201760, 2012). "Treatment of wild-type mice with obesity and insulin resistance induced by high-fat and high-sugar diet with this ligand resulted in improvement of insulin sensitivity but in a nonstatistically significant reduction in glucose levels." (PMID 22745632, 2012). "After dexamethasone was given to promote fetal lung maturation, insulin resistance increased, which meant that β-cell secretion was not sufficient to offset the insulin antagonistic hormones." (PMID 22536234, 2012). "Further support on this relationship is given by the low levels of apelin observed in type 1 diabetic subjects, where insulin secretion is absent and insulin-resistance is usually not present." (PMID 23227256, 2012). "This review is focused on the mechanistic aspects of the insulin-induced H2O2 signalling pathway in neurons and the factors affecting sit, which could promote the development of insulin resistance." (PMID 23730255, 2012). "Anti-TNFα therapy, through controlling inflammation, seems to improve insulin sensitivity in normal-weight RA patients with insulin resistance, but is not sufficient to achieving the same beneficial effect in obese RA patients with insulin resistance." (PMID 22765047, 2012). "As is clear from the results of this table, treatment with metformin significantly decreased insulin level and insulin resistance that this metabolic effect was not seen in other groups." (PMID 25246913, 2012). "Moreover, the IL6 global knockout mouse model is insulin-resistant, whilst the IL6 transgenic mouse is protected from diet-induced obesity and insulin-resistance." (PMID 22474579, 2012). "Although numerous studies have shown that insulin resistance precedes the development of hyperglycemia in patients that eventually develop T2DM, it is being recognized that T2DM only develops in insulin-resistant people displaying the onset of beta cell dysfunction." (PMID 22675572, 2012). "Animals from the MetS group were insulin-resistant at all ages, as compared to respective C and H groups although insulin resistance did not increase over time." (PMID 22897936, 2012).
Insulin resistance (continued). "In non-obese subjects, 6.2% of them were insulin resistant, and the best marker of insulin resistance was ALT/AST ratio, but serum HMW adiponectin, ALT, and hsCRP also discriminated insulin resistance." (PMID 23020992, 2012). "A constitutively active Akt (myr-Akt) redistributes GLUT4 to the plasma membrane in the absence of insulin and the Akt2 knockout mouse develops insulin resistance and type II diabetes." (PMID 27335671, 2012). "This was not a result of insulin resistance as these mice were more insulin sensitive than the high fat diet fed mice, as determined by the euglycemic-hyperinsulinemic clamp." (PMID 23201760, 2012). "Meanwhile, the first-stage insulin release peak was delayed with decreased AUCI from 0 to 10 min and increased AUCI from 10 to 60 min during IVIRT, which is the typical feature of the islet function in insulin resistance state." (PMID 23197974, 2012). "In mice lacking both kinin receptors, however, the increased insulin secretion can no further compensate the pronounced insulin resistance that accompanies aging in obB1B2KO mice, leading to severe glucose intolerance." (PMID 22829877, 2012). "Rather than becoming hyperglycemic, Asians with insulin resistance exhibit normal insulin levels or hypoinsulinemia, and easily progress from glucose intolerance to type 2 diabetes." (PMID 23270397, 2012). "It is now well accepted that the insulin-resistant state induces the mitogen-activated protein kinase pathway and increases MCP-1 secretion from adipocytes, indicating that MCP-1 potentiates the pathology of insulin resistance." (PMID 22496600, 2012). "The method itself does not appear to be sufficiently robust for an accurate diagnosis of insulin resistance; however, our findings suggest that the test can be helpful to identify individuals who are not insulin resistant." (PMID 22848216, 2012). "In the San Antonio Heart Study, insulin resistance as measured by the homeostasis model assessment (HOMA-IR) was related to CVD risk factors, whereas insulin secretion was not." (PMID 22720085, 2012). "Dexamethasone induced insulin resistance in both diabetic and nondiabetic subjects and resulted in an elevation in fasting glucose, insulin and HOMA2-IR homeostasis model assessment in the current study." (PMID 23241228, 2012). "In addition, HFD-induced increased white adipose tissue (WAT) participates in the induction of whole body insulin resistance, via increasing the secretion of the pro-inflammatory cytokine, TNF-α, which impairs insulin signaling." (PMID 22649556, 2012). "When cells are no longer able to compensate for insulin resistance by adequately increasing insulin production, impaired glucose tolerance (IGT) appears." (PMID 26557292, 2012). "The lack of an effect of re-feeding on the FFA levels in the HFD-fed control mice was not due to a reduction in food intake or low insulin levels but mainly due to their insulin resistance." (PMID 23024761, 2012). "Alternatives have been sought to simplify the measurement of insulin resistance and one is Homeostatic Model Assessment of insulin resistance (HOMA-IR), which uses fasting insulin and glucose levels to calculate insulin resistance and correlates reasonably with the results of clamping studies." (PMID 23020992, 2012). "Common insulin resistance/sensitivity indices were not assessed because a high proportion of the studied patients were receiving exogenous insulin." (PMID 23062182, 2012). "iii- We did not explore many important pathophysiological phenotypes, e.g. incretin role and liver vs peripheral insulin resistance, which are not measured by the state-of-art methods that we used to assess beta cell function and insulin sensitivity." (PMID 22427875, 2012). "Moreover, glutamine supplementation, which was shown to specifically induce insulin resistance in the adipose tissue of rats under HFD, also leads to amelioration of insulin action in other insulin responsive organs." (PMID 23024762, 2012).
Insulin resistance (continued). "GH-induced insulin resistance may develop from the increased FFA mobilization in the adipose tissue, which can affect liver insulin sensitivity and lead to insulin resistance and the up-regulation of PEPCK and G6Pase." (PMID 24281711, 2012). "None of the investigated SNPs showed any significant association with obesity (BMI, WHR), or glucose traits (FBG, 2 h glucose, fasting insulin, insulin resistance [HOMA-IR] and β-cell function [HOMA-B]) (data not shown)." (PMID 22623978, 2012). "In addition, plasma concentrations of glucose and cholesterol as well as serum insulin levels were increased in male mice on HFD, which, together with the observed impaired tolerance to glucose and insulin, indicate development of insulin resistance." (PMID 23049932, 2012). "First, the postchallenge responses of insulin and insulin resistance estimated by homeostasis model assessment (HOMA-IR) were not included in this study." (PMID 22397368, 2012). "Based on other reports, it was indicated that HCV infection may also impair the insulin-induced IRS-1, PI3K and Akt phosphorylation that lead to insulin resistance." (PMID 22721429, 2012). "Insulin increased P-eNOS/eNOS ratio in CD rats but not in CafD rats, indicating that CafD induces liver endothelial insulin resistance." (PMID 22509248, 2012). "Serum analyses revealed a ∼2-fold (p<0.01) increase in triglycerides and free fatty acids, and a ∼3-fold (p<0.01) increase in insulin levels, indicating insulin resistance; however, no significant cytokine profile alterations have been determined." (PMID 22363740, 2012). "It suggests that it is abnormalities of insulin secretion rather than changes in insulin resistance that is crucial for the development of DM2 in this population." (PMID 22927833, 2012). "In agreement with our hypothesis that increasing the lipogenic capacity of skeletal muscle can improve insulin sensitivity, the results of the present study indicate that DGAT1 overexpression did improve skeletal muscle insulin resistance." (PMID 21264296, 2011). "HMW adiponectin seems to be a better predictor of insulin resistance than total adiponectin; in particular, the ratio of HMW to total adiponectin or HMW to LMW may provide a better reflection of peripheral insulin sensitivity than total adiponectin alone." (PMID 21760816, 2011). "Insulin resistance refers to a suppressed or delayed response to insulin and is generally a post-receptor phenomenon, due to a defect in cells that respond to insulin, rather than on insulin production." (PMID 21276212, 2011). "In studies of animal models of insulin resistance, i.e. ob/ob mice and Gato-Kakazaki rats, focusing on hepatic Akt and aPKCs, insulin-activation of Akt but not aPKCs was impaired." (PMID 22087313, 2011). "It usually begins with insulin resistance, a condition in which fat, muscle, and liver cells do not use insulin properly." (PMID 21504591, 2011). "All four individuals were over-weight (BMI 28–34) and showed signs of insulin resistance (as measured by minimum fasting insulin>148 pmol/l and glucose>6 mmol/l), but their mean age was no different to non-heteroplasmic individuals at HVII." (PMID 21857921, 2011). "The development of a nongenetic mouse model for T2D involves establishment of insulin resistance, a period of compensatory insulin release to maintain glucose homeostasis." (PMID 22164157, 2011). "Some clinical data suggested that the polymorphisms affected the capacity of pancreatic β-cells to secrete insulin rather than aggravating insulin resistance, possibly by impaired β-cell proinsulin-processing." (PMID 21349175, 2011). "We recently showed that without dysregulated glucagon secretion, the combination of defective insulin secretion and peripheral insulin resistance was not sufficient to induce hyperglycemia in synaptotagmin-7 KO mice." (PMID 22046328, 2011).
Insulin resistance (continued). "In sharp contrast to TNFα negative effects on insulin action, adiponectin positively enhances insulin sensitivity, and hypoadiponectinemia accordingly leads to insulin resistance." (PMID 21941675, 2011). "Insulin resistance also occurs in lean individuals, however, and the mechanisms contributing to impaired insulin signaling in the absence of obesity are much less well characterized." (PMID 21589939, 2011). "To exclude that the presence of insulin-resistance or obesity could mask the possible effects of the APOC3 SNPs, we stratified our subjects on the basis of their insulin-resistance indices, insulin levels, or grade of obesity." (PMID 21663607, 2011). "Despite the fact that BALB.apoE-/- mice displayed significant insulin resistance on the Western diet, as evidenced by the lack of insulin response during the insulin tolerance test, they did not develop hyperglycemia." (PMID 22204493, 2011). "This insulin resistance is selective in the sense that it does not affect insulin action on aPKC-regulated lipogenic genes." (PMID 22087313, 2011). "Resistance to insulin-mediated glucose disposal is distributed continuously through the general population, but we have no measurement which identify a participant with insulin resistance or insulin sensitive." (PMID 21586120, 2011). "On the other hand, B6.apoE-/- mice did not have insulin resistance, as indicated on the insulin tolerance test, but they developed hyperglycemia, suggesting that a defect in insulin secretion is essential for the development of hyperglycemia in this model." (PMID 22204493, 2011). "Basal measures of peripheral insulin resistance (HOMA-IR) in the absence of infused insulin correlate with peripheral glucose disposal rate measured during a glucose-insulin clamp (~r = 0.88)." (PMID 22151886, 2011). "Although glucose intolerance in hyperthyroidism can be easily explained by hepatic insulin resistance without involvement of peripheral tissues, impaired insulin-stimulated peripheral glucose uptake has also been proven in some studies." (PMID 21941681, 2011). "In keeping with this hypothesis, blocking DRD2 by haloperidol induced insulin resistance in DR mice, whereas activation of DRD2 by bromocriptine tended to improve insulin sensitivity in DIO mice." (PMID 21603181, 2011). "This study demonstrates that in diabetic pigs insulin resistance for glucose utilization is accompanied by insulin hypersensitivity for non-essential AA utilization." (PMID 21605349, 2011). "Multiple studies have been performed detailing the relationship between insulin resistance and NAFLD and have shown that disordered insulin regulation results in multiple, altered metabolic pathways which ultimately lead to fat deposition and inflammation in the liver." (PMID 21645344, 2011). "Taken together, our data indicate that NAMPT expression in subcutaneous adipocytes is not regulated by high insulin and glucose concentrations that represent common features of insulin resistance and type 2 diabetes." (PMID 21687707, 2011). "An increase in β-cell volume in insulin-resistant obese non-diabetic humans suggests that an islet compensation likely occurs in humans as an initial adaptive response to insulin resistance, to delay the onset of hyperglycemia in type 2 diabetes." (PMID 22140505, 2011). "In both groups, thus regardless of treatment, insulin levels and insulin resistance significantly improved during follow-up." (PMID 22035351, 2011). "The European Group for the Study of Insulin Resistance take a more restricted view, defining insulin resistance as the insulin sensitivity index of the lowest 10% of a nonobese, nondiabetic, normotensive white population." (PMID 21251282, 2011). "While blood glucose levels were not different, plasma insulin levels were significantly elevated in the HF animals, indicating the presence of insulin resistance (*p<0.05 by Student's t-test)." (PMID 21969871, 2011).
Insulin resistance (continued). "Insulin sensitivity was not assayed in this study,thus the relationship between plasma homocysteinelevel and insulin resistance was notdetermined." (PMID 24851177, 2011). "Consistent with the notion, our recent study showed that in the absence of dysregulated glucagon secretion, the combination of defective insulin secretion and peripheral insulin resistance was not sufficient to induce hyperglycemia in synaptotagmin-7 KO mice." (PMID 22046328, 2011). "The associations observed in GrOW suggest that those women who carried the Hap6 haplotype showed some insulin resistance, since as they had higher plasma insulin, but their glucose levels do not differ significantly from the other haplotypes." (PMID 20227263, 2011). "It would be of considerable benefit for clinicians if other standardized measures are available for predicting insulin resistance without the need for direct measurements of fasting insulin." (PMID 22004541, 2011). "Infusion of FFA in subjects with normal glucose tolerance has been shown to increase the expression of ECM genes in muscle coincident with a decrease in insulin sensitivity; furthermore, animal studies indicate that ECM expansion contributes to insulin resistance." (PMID 22194858, 2011). "Seven type 2 diabetic patients with severe insulin resistance (mean insulin dose 195 IU/day) were compared with seven age matched type 2 diabetic patients who did not require insulin treatment, and with an age matched healthy control group." (PMID 22114711, 2011). "Thirdly, it could be a possible source of bias as to the facts that fasting insulin and HOMA-IR was used as a surrogate marker of insulin resistance, instead of the gold standard of the hyperinsulinemic euglycemic clamp." (PMID 21176200, 2010). "Consistent with the absence of any observable effect on functional measures of insulin sensitivity, no signs of insulin resistance at the molecular level are observed from NButGT treatment." (PMID 20851344, 2010). "In insulin resistance, a condition related to type 2 diabetes, insulin no longer leads to an efficient translocation of GLUT4 towards the cell surface." (PMID 21187969, 2010). "Therefore, methods such as fasting insulin level, fasting glucose/insulin ratio (FGIR), homeostasis model assessment for insulin resistance (HOMA−IR) and quantitative insulin−sensitivity check index (QUICKI) are frequently used in population screening." (PMID 21274322, 2010). "It is possible that hepatic insulin resistance, reflected primarily by fasting glucose and insulin concentrations, had not developed after only 8 weeks." (PMID 21034486, 2010). "Taken together, we have demonstrated the presence of a factor (or several factors) in serum that induce GLUT4 translocation in a manner that is largely independent of insulin and insulin signaling and whose effects are fully maintained in insulin resistance." (PMID 21187969, 2010). "While we did observe a significant attenuation in glucose and insulin responses when RS4XL was incorporated into the bar, it is not possible to know whether the same effects would occur in individuals with insulin resistance or other metabolic conditions." (PMID 20798767, 2010). "The decision to define insulin resistance this way was based on the approach taken by the EGIR to define hyperinsulinemia as being in the top quartile of fasting insulin values in a non-diabetic population." (PMID 21134291, 2010). "Resistance to insulin-mediated glucose disposal is distributed continuously through the general population, and we have no criterion with which to identify a participant as being insulin resistance or insulin sensitive." (PMID 21134293, 2010). "High H2S level in streptozotocin-induced diabetic rat and ZDF rat is responsible for the low level of insulin and it does not have any role in development of insulin resistance." (PMID 21264117, 2010).